ZNF486 (zinc finger protein 486)
Description:
May be involved in transcriptional regulation.
Synonyms: KRBO2; MGC2396
Tractability: PROTAC: ubiquitination databases record sites on it.
Gene: Protein-coding gene on chromosome 19 (20,167,214 to 20,200,488, forward strand). Ensembl gene ENSG00000256229.
Subcellular location: Nucleus
Pathways (Reactome):
Gene expression (Transcription): Generic Transcription Pathway
Gene Ontology:
Molecular function: DNA-binding transcription factor activity, RNA polymerase II-specific; RNA polymerase II cis-regulatory region sequence-specific DNA binding
Biological process: regulation of DNA-templated transcription; regulation of transcription by RNA polymerase II
Cellular component: extracellular exosome; nucleus
Genetic constraint (gnomAD): Loss-of-function variants: 11 observed, 10.07 expected, observed/expected ratio (o/e) 1.09, 90% interval 0.68 to 1.74. The synonymous counts are far from expectation, so gnomAD's model fits this gene poorly and the ratio says little. Missense variants: 727 observed, 550.61 expected, observed/expected ratio (o/e) 1.32, 90% interval 1.24 to 1.4. Synonymous variants: 230 observed, 182.98 expected, observed/expected ratio (o/e) 1.26, 90% interval 1.13 to 1.4.
Homologues: Orthologues: chimpanzee ZNF486 (98% identical). Paralogues in human: ZNF506 (72% identical), ZNF90 (70% identical), ZNF85 (69% identical), ZNF708 (68% identical), ZNF726 (67% identical), ZNF724 (67% identical), ZNF93 (67% identical), ZNF429 (66% identical), ZNF681 (66% identical), ZNF728 (65% identical), ZNF254 (65% identical), ZNF716 (63% identical), and 164 more.
Diseases named in the same sentence as ZNF486 in open-access papers:
ZNF486 is named in the same sentence as 3 diseases in open-access papers, as found by Europe PMC text mining. Sharing a sentence is not in itself a finding about the gene and the disease. The quoted sentences say what the papers report.
breast carcinoma (2 papers, 2022 to 2024). "ZNF486 codes for a zinc-finger protein that has been described as a potential prognosis marker in breast cancer patients, however more data would be needed to characterize its specific function in breast cancer cells." (PMID 39239354, 2024). "Interestingly, ZNF486 was reported to reliably predict the prognosis of breast cancer patients, rendering it a promising candidate for further investigation as a PRMT1 circRNAs target." (PMID 35885916, 2022).
myeloma (1 paper, 2020). "Moreover, a six-gene risk score model (ZNF486, EPHA5, RP11.326C3.15, DUSP6, DUSP10, and TRIAP1) for the prognostic prediction of PI-treated myeloma patients was developed by the random survival forest variable hunting (RSF-VH) algorithm." (PMID 33344452, 2020).
infection (2 papers, 2024). The state of being infected such as from the introduction of a foreign agent such as serum, vaccine, antigenic substance or organism. "When compared to productive infection with HIV-1YU2, the proviruses in Chr22 HSat3 and ZNF486 were expressed at >100 and >27,000-fold lower levels, respectively." (PMID 39141127, 2024). "When compared to productive infection with HIV-1YU2, the proviruses in ATP2B4 and ZNF486 were expressed at >100 and >27,000-fold lower levels respectively." (PMID 38746186, 2024).